TRIM39 (tripartite motif containing 39)
Description:
[Isoform 1]: E3 ubiquitin-protein ligase. May facilitate apoptosis by inhibiting APC/C-Cdh1-mediated poly-ubiquitination and subsequent proteasome-mediated degradation of the pro-apoptotic protein MOAP1. Regulates the G1/S transition of the cell cycle and DNA damage-induced G2 arrest by stabilizing CDKN1A/p21. Positively regulates CDKN1A/p21 stability by competing with DTL for CDKN1A/p21 binding, therefore disrupting DCX(DTL) E3 ubiquitin ligase complex-mediated CDKN1A/p21 ubiquitination and degradation. [Isoform 2]: Regulates the G1/S transition of the cell cycle and DNA damage-induced G2 arrest by stabilizing CDKN1A/p21. Positively regulates CDKN1A/p21 stability by competing with DTL for CDKN1A/p21 binding, therefore disrupting DCX(DTL) E3 ubiquitin ligase complex-mediated CDKN1A/p21 ubiquitination and degradation. Negatively regulates the canonical NF-kappa-B signaling pathway via stabilization of CACTIN in an ubiquitination-independent manner.
Synonyms: RNF23; TFP; TRIM39B
Tractability: Small molecule: it has a binding pocket of medium quality. PROTAC: UniProt records ubiquitination sites on it; ubiquitination databases record sites on it.
Gene: Protein-coding gene on chromosome 6 (30,325,880 to 30,344,265, forward strand). Ensembl gene ENSG00000204599.
Subcellular location: Cytoplasm, cytosol (Isoform 1); Mitochondrion; Nucleus; Nucleus (Isoform 2)
Subcellular location (Human Protein Atlas): Cytosol
Pathways (Reactome):
Immune System: Antigen processing: Ubiquitination & Proteasome degradation
Gene Ontology:
Molecular function: identical protein binding; protein binding; ubiquitin protein ligase activity; zinc ion binding
Biological process: mitotic G2 DNA damage checkpoint signaling; negative regulation of canonical NF-kappaB signal transduction; negative regulation of proteasomal ubiquitin-dependent protein catabolic process; negative regulation of ubiquitin-dependent protein catabolic process; positive regulation of apoptotic signaling pathway; protein stabilization; regulation of cell cycle G1/S phase transition; innate immune response; regulation of gene expression; protein ubiquitination
Cellular component: cytosol; mitochondrion; nucleus; cytoplasm
Genetic constraint (gnomAD): Loss-of-function variants: 5 observed, 54.87 expected, observed/expected ratio (o/e) 0.0911, 90% interval 0.047 to 0.19. The synonymous counts are far from expectation, so gnomAD's model fits this gene poorly and the ratio says little. Missense variants: 310 observed, 650.17 expected, observed/expected ratio (o/e) 0.48, 90% interval 0.43 to 0.52. Synonymous variants: 196 observed, 248.27 expected, observed/expected ratio (o/e) 0.79, 90% interval 0.7 to 0.89.
Homologues: Orthologues: chimpanzee TRIM39 (99% identical), macaque RPP21 (99% identical), pig TRIM39 (99% identical), rabbit TRIM39 (99% identical), guinea pig TRIM39 (98% identical), mouse Trim39 (98% identical), rat Trim39 (98% identical). Paralogues in human: TRIM11 (40% identical), TRIM58 (38% identical), TRIM27 (38% identical), TRIM41 (38% identical), TRIM21 (37% identical), TRIM17 (35% identical), TRIM10 (34% identical), TRIM7 (34% identical), TRIM4 (33% identical), TRIML1 (33% identical), TRIM60 (33% identical), TRIM75 (33% identical), and 68 more.
Diseases named in the same sentence as TRIM39 in open-access papers:
TRIM39 is named in the same sentence as 18 diseases in open-access papers, as found by Europe PMC text mining. Sharing a sentence is not in itself a finding about the gene and the disease. The quoted sentences say what the papers report.
Behcet disease (2 papers, 2020 to 2022). A chronic, relapsing, multisystemic vasculitis characterized by mucocutaneous lesions, as well as articular, vascular, ocular and central nervous system manifestations. "TRIM39 encodes for a ring finger protein associated with diseases including Behcet’s syndrome; it regulates p21 and plays an important role in determining cell fate." (PMID 35945619, 2022). "The TRIM39 or TRIM39-RPP21 locus is associated with Behcet’s disease, a chronic inflammatory autoimmune disease." (PMID 33311639, 2020).
colorectal cancer (2 papers, 2021 to 2023). A primary or metastatic malignant neoplasm that affects the colon or rectum. "TRIM39 deficiency can inhibit tumour progression and autophagy in colorectal cancer by inhibiting Rab7 activity." (PMID 38037161, 2023). "The biological function of TRIM39, a member of TRIM family, remains largely unexplored in cancer, especially in colorectal cancer (CRC)." (PMID 33846303, 2021).
Hypertension (2 papers, 2025). The presence of chronic increased pressure in the systemic arterial system. "There were several genes affected by high-intensity interval training during HFD hypertension, which were Trim39, Nr4a1, Plekhf1, Tgm2, Lgals1, Egr1, and Atf3." (PMID 41516177, 2025).
ovarian carcinoma (2 papers, 2020 to 2022). A malignant neoplasm originating from the surface ovarian epithelium. "Trim39 was also found to be a biomarker for early diagnosis of ovarian cancer and to regulate cell cycle progression and DNA damage responses." (PMID 35833210, 2022).
viral infections (2 papers, 2021 to 2022). "In this study, TRIM39 was up-accumulated at four time points after virus infection; thus, TRIM39 expression may be induced by IFN." (PMID 34113672, 2021).
breast carcinoma (1 paper, 2022). "In ER+ breast cancer, TRIM39 and TRIM29 knockdown significantly suppresse ER+ breast cancer cell proliferation." (PMID 36261847, 2022).
hepatoma (1 paper, 2022). "Current findings suggested that PHOSPHO2-KLHL23, TSNAX-DISC1, TRIM39 and RPP21 were associated with cell migration in SOF-treated hepatoma cells with and without HCV infection." (PMID 35833210, 2022). "The present results indicated that PHOSPHO2-KLHL23, TSNAX-DISC1, TRIM39 and RPP21 were associated with cell proliferation in SOF-treated hepatoma cells with and without HCV infection." (PMID 35833210, 2022).
insomnia (1 paper, 2024). A sleep disorder characterized by difficulty in falling asleep and/or remaining asleep. "Of these genes, TRIM39, LINC02595, DKACD, and TCF7L2 were previously associated with OSA or insomnia in genome-wide association studies (GWAS)." (PMID 39457448, 2024).
renal fibrosis (1 paper, 2024). A final common manifestation of a wide variety of chronic kidney diseases characterized by glomerulosclerosis and tubulointerstitial fibrosis. "Consistent with human kidney specimens, TRIM39 expression was markedly increased in renal fibrosis models." (PMID 38195664, 2024). "However, the role of TRIM39 in renal fibrosis and its underlying mechanisms still remain unclear." (PMID 38195664, 2024). "The current study revealed a previously unrecognized biological function of TRIM39 in aggravating renal fibrosis." (PMID 38195664, 2024). "Our study was the first to demonstrate the expression of TRIM39 was increased in renal fibrosis, while PRDX3 was decreased." (PMID 38195664, 2024). "Meanwhile, TRIM39 participated in the regulation of renal fibrosis through interacting with PRDX3 and mediating its ubiquitination." (PMID 38195664, 2024). "We found that PRDX3 ubiquitination was markedly increased in renal fibrosis models and it was significantly weakened when TRIM39 was silenced." (PMID 38195664, 2024). "In conclusion, these results revealed that TRIM39 induced PRDX3 degradation at lysine K73 and K149 through K48-linked ubiquitin to aggravate renal fibrosis." (PMID 38195664, 2024). "Future development of TRIM39 inhibitors or PRDX3 agonists will be a crucial direction for renal fibrosis therapy." (PMID 38195664, 2024). "To explore the TRIM39 function during renal fibrosis development, we focused on oxidative stress as it played essential role in renal fibrosis." (PMID 38195664, 2024). "In this study, we investigated the role of TRIM39 in renal fibrosis and its molecular mechanism." (PMID 38195664, 2024). "And it was found that the inhibition of ROS production could significantly reduce renal fibrosis, which inspired us to further investigate the targets and molecular mechanisms of TRIM39 regulating oxidative stress." (PMID 38195664, 2024). "We found an upregulated expression of TRIM39 in renal fibrosis human specimens and models." (PMID 38195664, 2024). "We found that TRIM39 expression was significantly increased in fibrotic kidney tissue compared with paracancerous normal tissue, which suggested that TRIM39 might be involved in the formation of renal fibrosis." (PMID 38195664, 2024). "Since proteasomal degradation of proteins was mostly related to ubiquitination modification, we speculated that TRIM39 might aggravate renal fibrosis by regulating ubiquitination degradation of PRDX3." (PMID 38195664, 2024). "In conclusion, these results demonstrated that TRIM39 might aggravate UUO-induced renal fibrosis by enhancing the production of inflammation factors." (PMID 38195664, 2024). "Since TGF-β1 mediated the activation of phosphorylation of Smad family, especially Smad3, was a classic pathway for its induction of renal fibrosis, we speculated that this may be related to its up-regulation of TRIM39 expression." (PMID 38195664, 2024). "In addition, TRIM39 knockdown was found efficient for alleviating renal fibrosis in both UUO mice and HK-2 cells." (PMID 38195664, 2024). "To further investigate whether TRIM39 regulated renal fibrosis and oxidative stress through PRDX3, we knocked down these two genes in HK-2 cells." (PMID 38195664, 2024). "Tripartite motif-containing (TRIM) family proteins have been shown to be involved in fibrotic diseases, but whether TRIM39 plays a role in renal fibrosis remain unexplored." (PMID 38195664, 2024). "In this study, we found that TRIM39 expression was elevated in UUO, and its knockout alleviated UUO-mediated renal fibrosis." (PMID 38195664, 2024). "To further explore the relationship between TRIM39 and PRDX3 in renal fibrosis, we performed a tail-vein injection of the shPRDX3 in CKO mice and TRIM39Flox/Flox mice." (PMID 38195664, 2024). "In summary, we first found that TRIM39 induced the ubiquitination degradation of PRDX3 through the K48 chain, which resulted in the ROS accumulation, increased inflammatory cytokine production and renal fibrosis." (PMID 38195664, 2024).
renal fibrosis (continued). "Furthermore, we also demonstrated that TRIM39 reduced H2O2 clearance through ubiquitination degradation of PRDX3, leading to ROS accumulation and aggravating renal fibrosis." (PMID 38195664, 2024). "Interestingly, the protective effect of TRIM39 knockout on UUO was reversed by down-regulation of PRDX3 expression, which indicated that TRIM39 might regulate renal fibrosis and oxidative stress in a PRDX3 manner." (PMID 38195664, 2024). "Mechanistically, we demonstrated that TRIM39 interacted with PRDX3 directly and induced ubiquitination degradation of PRDX3 at K73 and K149 through the K48 chain, which resulted in ROS accumulation and increased inflammatory cytokine generation, and further aggravated renal fibrosis." (PMID 38195664, 2024). "However, the role of TRIM39 in renal fibrosis has not been studied." (PMID 38195664, 2024).
schizophrenia (1 paper, 2019). A major psychotic disorder characterized by abnormalities in the perception or expression of reality. "Moreover, four DMRs were located at genes (VPS52, TCIRG1, and TRIM39) that were found to be differentially methylated in the largest schizophrenia (SCZ) whole-blood epigenome-wide association study (EWAS) to date." (PMID 31639064, 2019).
serous ovarian cancer (1 paper, 2021). "Three auto-antibodies, against NUDT11, PVR, and TRIM39, were consistently selective for serous ovarian cancer with individual sensitivities ranging from 14.7% to 32.4% at 96% specificity." (PMID 33672007, 2021).
Ureteral obstruction (1 paper, 2024). Obstruction of the flow of urine through the ureter. "TRIM39 expression was analyzed in patients’ specimens, HK-2 cells and unilateral ureteral obstruction (UUO) mice were used for functional and mechanistic studies." (PMID 38195664, 2024).
cancer (4 papers, 2020 to 2022). A tumor composed of atypical neoplastic, often pleomorphic cells that invade other tissues. "Two non-human leukocyte antigen (HLA) genes are E3 ubiquitin ligases, TRIM31 and TRIM39, having a role in the innate immune response and implicating the importance of host Epstein-Barr virus interactions in this cancer." (PMID 33311639, 2020).
infection (4 papers, 2022 to 2023). The state of being infected such as from the introduction of a foreign agent such as serum, vaccine, antigenic substance or organism. "Full complementation was observed for the expression levels of TRIM39, SARM1, SLC25A26, NDUFA8 and DTYMK by infection with C∆tbcm, which showed similar trends as wild-type BCG infection." (PMID 38110948, 2023). "The most induced genes after NNV infection with the wt virus were VRGs, particularly RTP3, SACS, and TRIM39." (PMID 35215144, 2022).
tumor (4 papers, 2020 to 2023). "Here we found that TRIM39 was upregulated in CRC tumor tissues and associated with poor clinical outcomes of CRC patients." (PMID 33846303, 2021). "In this study, we show that TRIM39 is upregulated in tumor tissues compared to adjacent normal tissues and associated with poor prognosis in CRC." (PMID 33846303, 2021). "Rab7 overexpression reversed in vivo tumor suppression caused by TRIM39 knockdown." (PMID 33846303, 2021). "In conclusion, we demonstrate for the first time that TRIM39 regulates autophagy and tumor progression through modulating Rab7 activity." (PMID 33846303, 2021). "In NPC, TRIM39 functionally affects cell proliferation, epithelial–mesenchymal transition, and metastasis and clinically correlates significantly with tumor size, stage, and metastasis." (PMID 33311639, 2020). "Consistently, in vivo, TRIM39 knockdown inhibited tumor growth." (PMID 33846303, 2021). "Second, NGS and TCGA data analysis revealed that several SOF-upregulated genes, including PHOSPHO2-KLHL23, TSNAX-DISC1, TRIM39 and RPP21, were also higher in tumor compared with non-tumor parts in patients with HCC." (PMID 35833210, 2022). "Among these genes, PHOSPHO2, KLHL23, TRIM39, TSNAX-DISC1 and RPP21 expression were significantly elevated in the tumor tissues compared with the non-tumor tissues of HCC according to TCGA database." (PMID 35833210, 2022). "Rab7 knockdown inhibited tumor growth and CRC cell migration in vitro and in vivo, similar to the phenotypes observed for TRIM39 knockdown." (PMID 33846303, 2021). "This study found that several genes including PHOSPHO2, KLHL23, TSNAX-DISC1, TRIM39 and RPP21 were upregulated by SOF and the expression levels of these genes were higher in tumor than in non-tumor parts of patients with HCC according to the TCGA database." (PMID 35833210, 2022).
infectious disease (1 paper, 2011). A disorder directly resulting from the presence and activity of a microbial, viral, or parasitic agent in humans. "The mRNA expression level was the highest in spleen and with a lower expression in liver, brain, and lung, suggesting that TRIM39 protein might be an interesting candidate affecting infectious disease." (PMID 21747707, 2011). "In chicken, a cluster of TRIM-B30.2 genes including TRIM39 in the chicken MHC B locus has been identified flanking the chicken BF/BL region and may be a candidate for genes affecting infectious disease." (PMID 21747707, 2011).
TRIM39 also shares sentences with these, for which no sentence is quoted: bacterial infections (1 paper); nasopharyngeal carcinoma (1).